DDX53 (DEAD-box helicase 53)
Synonyms: CT26; CAGE
Tractability: Small molecule: a structure with a bound ligand is known. PROTAC: ubiquitination databases record sites on it.
Gene: Protein-coding gene on chromosome X (22,999,960 to 23,003,589, forward strand). Ensembl gene ENSG00000184735.
Subcellular location: Nucleus
Subcellular location (Human Protein Atlas): Nucleoplasm; Cytosol; Nucleoli
Gene Ontology:
Molecular function: protein binding; ATP binding; ATP hydrolysis activity; nucleic acid binding; RNA binding; RNA helicase activity
Cellular component: nucleoplasm; nucleus
Homologues: Orthologues: chimpanzee DDX53 (97% identical), macaque DDX53 (90% identical). Paralogues in human: DDX43 (61% identical), DDX17 (32% identical), DDX5 (32% identical), DDX46 (29% identical), DDX42 (29% identical), DDX41 (27% identical), DDX4 (27% identical), DDX3X (26% identical), DDX23 (26% identical), DDX3Y (26% identical), DDX59 (24% identical), DDX52 (24% identical), and 26 more.
Diseases named in the same sentence as DDX53 in open-access papers:
DDX53 is named in the same sentence as 72 diseases in open-access papers, as found by Europe PMC text mining. Sharing a sentence is not in itself a finding about the gene and the disease. The quoted sentences say what the papers report.
breast cancer (9 papers, 2015 to 2025). A primary or metastatic malignant neoplasm involving the breast. "Cancer-specific antigens, DDX43 (helicase antigen gene, HAGE) and DDX53 (cancer-associated gene, CAGE), are overexpressed in almost all cancers, while DDX20 (dp103) is highly expressed in breast cancer." (PMID 36761420, 2022).
autism (1 paper, 2023). Persistent deficits in social interaction and communication and interaction as well as a markedly restricted repertoire of activity and interest as well as repetitive patterns of behavior. "Males who carry chromosome microdeletions of PTCHD1 antisense long non-coding RNA (PTCHD1-AS)/DEAD-box helicase 53 (DDX53) have ASD, or a sub-clinical form called Broader Autism Phenotype." (PMID 36635662, 2023).
gynecological cancer (1 paper, 2023). "DDX53, also known as cancer/testis antigen cancer-associated gene (CAGE), is only expressed in normal testes, suggesting it is a possible target in gynecological cancer therapy." (PMID 37763070, 2023).
Nance-Horan syndrome (1 paper, 2015). A syndrome characterized by the association in male patients of congenital cataracts with microcornea, dental anomalies and facial dysmorphism. "We considered an X-linked recessive model (female child less severe than male) and identified variants were inNHS (Nance-Horan syndrome),DDX53, WAS, andTREX2; four variants inRPGR." (PMID 26535115, 2015).
nasopharyngeal carcinoma (1 paper, 2023). A carcinoma arising from the nasopharyngeal epithelium. "In nasopharyngeal carcinoma cells (CNE1), a paclitaxel-resistant clone overexpressed P-gp as well as the regulatory protein DDX53 (DEAD-Box helicase 53)." (PMID 37629489, 2023).
Thrombocytopenia (1 paper, 2018). A reduction in the number of circulating thrombocytes.
tumor (610 papers, 2007 to 2026). "Earlier explorations have shown that definite RNA helicases including DDX53 (CAGE) are involved in tumor cell progress and proliferation in numerous types of malignancies." (PMID 37200388, 2023).
cancer (94 papers, 2009 to 2025). A tumor composed of atypical neoplastic, often pleomorphic cells that invade other tissues. "Previously, miRNAs, including miR-200b, miR-217, and miR-335, were reported to regulate DDX53 levels in different cancer cells." (PMID 37763070, 2023). "Cancer/testis antigen DDX53 is found in the sera of various cancers, and the expression of DDX53 is regulated by methylation." (PMID 37763070, 2023). "To examine DDX53 functions in EC cells, we conducted DDX53 OE and KD studies in HEC-1 and SNU-539 cells, respectively, and showed that DDX53 OE in HEC-1 cells increased key cancer phenotypes, whereas DDX53 KD in SNU-539 cells decreased them." (PMID 37763070, 2023). "Although DDX53 expression is restricted to normal testicular germline cells, upregulated DDX53 levels were reported in several cancer cell lines." (PMID 37763070, 2023). "Other family members such as DDX51, DDX5, and DDX53 play important roles in several cancers." (PMID 38807916, 2024). "In several cancers, DDX53 is reported to be controlled by miRNAs, which suggests it may be a promising candidate in anti-cancer drug development." (PMID 37763070, 2023). "Thus, DDX53 may regulate EC progression and metastasis by inducing epithelial polarity loss and mesenchymal phenotype acquisition, or EMT, in cancer cells." (PMID 37763070, 2023). "Thus, DDX53 putatively regulated EC progression and metastasis via epithelial-mesenchymal transition (EMT), where cancer cells lost epithelial polarity and transitioned to a mesenchymal phenotype." (PMID 37763070, 2023).
DDX53 also shares sentences with these, for which no sentence is quoted: colon carcinoma (113 papers); colorectal cancer (33); infection (21); Cachexia (12); colorectal tumor (9); gastric cancer (9); melanoma (9); colon adenocarcinoma (5); gastritis (4); lung carcinoma (4); duodenal ulcer (3); fibrosarcoma (3); metastatic disease (3); Splenomegaly (3); triple-negative breast carcinoma (3); bowel cancer (2); chronic gastritis (2); endometrial cancer (2); gastric ulcer (2); Lewis lung carcinoma (2); liver cancer (2); lymphoma (2); multiple myeloma (2); pancreatic cancer (2); renal carcinoma (2); viral infection (2); acute myeloid leukemia (1); adenocarcinoma (1); adenoma (1); Ascites (1).
A further 34 diseases each share a sentence with DDX53 in 1 paper.